NDUFA13 (NADH:ubiquinone oxidoreductase subunit A13)
Description:
Accessory subunit of the mitochondrial membrane respiratory chain NADH dehydrogenase (Complex I), that is believed not to be involved in catalysis. Complex I functions in the transfer of electrons from NADH to the respiratory chain. The immediate electron acceptor for the enzyme is believed to be ubiquinone. Involved in the interferon/all-trans-retinoic acid (IFN/RA) induced cell death. This apoptotic activity is inhibited by interaction with viral IRF1. Prevents the transactivation of STAT3 target genes. May play a role in CARD15-mediated innate mucosal responses and serve to regulate intestinal epithelial cell responses to microbes.
Synonyms: GRIM-19; GRIM19; CDA016; CGI-39; B16.6; MC1DN28
Tractability: Small molecule: an approved drug acts on it; a structure with a bound ligand is known. Antibody: UniProt predicts a signal peptide or a membrane-spanning region. PROTAC: ubiquitination databases record sites on it; its protein half-life has been measured; a small molecule that binds it is known.
Target class: Enzyme; Oxidoreductase
Gene: Protein-coding gene on chromosome 19 (19,515,736 to 19,529,054, forward strand). Ensembl gene ENSG00000186010.
Subcellular location: Mitochondrion inner membrane; Nucleus
Subcellular location (Human Protein Atlas): Mitochondria
Pathways (Reactome):
Metabolism: Complex I biogenesis; Respiratory electron transport
Metabolism of proteins: Mitochondrial protein degradation
Gene Ontology:
Molecular function: protein binding; ATP binding; endopeptidase activator activity
Biological process: cellular response to interferon-beta; cellular response to retinoic acid; mitochondrial respiratory chain complex I assembly; negative regulation of DNA-templated transcription; positive regulation of execution phase of apoptosis; positive regulation of protein catabolic process; protein insertion into mitochondrial inner membrane; aerobic respiration; proton motive force-driven mitochondrial ATP synthesis
Cellular component: cytoplasm; mitochondrial inner membrane; mitochondrial membrane; mitochondrion; nucleoplasm; nucleus; respiratory chain complex; respiratory chain complex I
Genetic constraint (gnomAD): Loss-of-function variants: 17 observed, 19.6 expected, observed/expected ratio (o/e) 0.87, 90% interval 0.59 to 1.3. The upper end of that interval is the gene's LOEUF score, 1.3, which puts it in group 5 of 6, group 1 being the genes least tolerant of losing a copy. Missense variants: 228 observed, 206.07 expected, observed/expected ratio (o/e) 1.11, 90% interval 0.99 to 1.24. Synonymous variants: 87 observed, 80.07 expected, observed/expected ratio (o/e) 1.09, 90% interval 0.91 to 1.3.
Gene-disease validity (ClinGen):
ClinGen rates the evidence that NDUFA13 causes each of these diseases.
Leigh syndrome (autosomal recessive): Moderate. A progressive neurological disease defined by specific neuropathological features associating brainstem and basal ganglia lesions.
mitochondrial disease (autosomal recessive): Moderate.
Homologues: Orthologues: chimpanzee NDUFA13 (99% identical), rat Yjefn3 (85% identical), mouse Ndufa13 (83% identical), dog NDUFA13 (78% identical), rat Ndufa13-ps1 (78% identical), pig NDUFA13 (76% identical), guinea pig NDUFA13 (70% identical), tropical clawed frog ndufa13 (68% identical), Caenorhabditis elegans ndua-13 (31% identical), Drosophila melanogaster ND-B16.6 (31% identical).